SQSTM1 (sequestosome 1)
Diseases named in the same sentence as SQSTM1 in open-access papers (continued):
Sharing a sentence is not in itself a finding about the gene and the disease.
tauopathy (8 papers, 2016 to 2024). Neurodegenerative disorders involving deposition of abnormal tau protein isoforms (tau proteins) in neurons and glial cells in the brain. "The aggregation-prone protein tau, encoded by the MAPT gene, has been found to interact with SQSTM1 in both human brain tissue with tauopathies and in murine transgenic tauopathies models." (PMID 39098523, 2024). "Recently, we reported that the genetic ablation of p62/SQSTM1, a ubiquitinated cargo receptor for selective autophagy, exacerbates tau pathologies, neuronal death, and neuroinflammation in a mouse model of tauopathy (PS19 mice)." (PMID 37746832, 2024). "It was reported that the autophagic marker p62/SQSTM1 accumulates and colocalizes with hyperphosphorylated tau in human tauopathies." (PMID 28874186, 2017). "Altogether, the accumulation of p62/SQSTM1 and its colocalization with hyperphorylated tau suggest defective protein clearance in tauopathy patients, which is in accordance with previous studies." (PMID 26936765, 2016). "Interestingly, overexpression of p62/SQSTM1 reduces pathological tau and spreading in tauopathy mouse models." (PMID 34419832, 2021). "To investigate whether the protein clearance was defective in patients with tauopathies, we analysed the p62/SQSTM1 protein by immunostaining." (PMID 26936765, 2016). "Thus, it is tempting to speculate that the accumulation of hyperphosphorylated tau, p62/SQSTM1 and LC3 in threads in the tauopathy patients are, at least partly, due to impaired axonal transport." (PMID 26936765, 2016).
Cognitive impairment (7 papers, 2018 to 2025). Abnormal cognition is characterized by deficits in thinking, reasoning, or remembering. "Among patients with SQSTM1 mutations, cognitive impairment was variable." (PMID 40649976, 2025). "Two heterozygous pathogenic variants in SQSTM1 and RORA was detected in patient HA72, a 61 year-old female diagnosed with upper limb spasticity, ataxic gait and mild cognitive impairment." (PMID 40208338, 2025). "Coinciding with these studies, the current findings revealed defective hippocampal autophagy in cadmium-induced cognitive deficit as manifested by a spike of SQSTM-1/p62." (PMID 37765022, 2023). "However, it is important to mention that the results from patients with PSEN1, SQSTM1, VCP, and ANXA11 mutations highlight distinct patterns of cognitive impairment, reflecting both shared and gene-specific features of neurodegeneration." (PMID 40649976, 2025). "The cognitive impairment in family 1 may reflect the previously reported deleterious effects of the TIA1 and SQSTM1 variants on brain, as mutations in both genes have been identified in ALS and FTD." (PMID 29599744, 2018). "Cognitive impairment was identified in 4 (13%) patients (3 VCP and 1 SQSTM1 + TIA1) through short cognitive evaluation and formal neuropsychological testing." (PMID 36861178, 2023). "Thirteen percent of patients manifested cognitive impairment (VCP and SQSTM1 + TIA1)." (PMID 36861178, 2023).
COVID-19 (7 papers, 2021 to 2025). A disease caused by infection with severe acute respiratory syndrome coronavirus 2. "The increase in the expression of SQSTM1 in patients who had COVID-19, together with five central genes associated with COVID-19." (PMID 41472277, 2025). "After intersecting the list of top 10 genes from each algorithm with the help of an upset diagram, it was determined that the SQSTM1/P62 gene is a common central gene for severe COVID-19-associated cancer." (PMID 41472277, 2025). "Xia and colleagues showed that the decrease in circulating levels of LC3 (in patients of any age) and SQSTM1 (in patients up to 50 years old) is associated with the development of moderate-to-severe COVID-19." (PMID 34440791, 2021). "Notably, the autophagy-related gene SQSTM1/P62 was recognized as a distinctive hub gene within the severe COVID-19 patients, interacting with pivotal genes associated with inflammation, apoptosis, and cancer advancement." (PMID 41472277, 2025). "Notably, our identification of H3-5/H3F3C, H3C13/HIST2H3D, JUN, EGR1, NOTCH1, and SQSTM1/P62 as central hub genes unique to the COVID-19 signature links this pro-oncogenic state to a specific molecular target that regulates inflammation, autophagy, and cancer progression." (PMID 41472277, 2025). "This study shows sex differences in stress proteins p62/SQSTM1, ERK1/2, and GSK3α/β, along with innate immunity and inflammation in hearts of ferrets infected with SARS-CoV-2, identifying mechanisms of COVID-19 cardiac injury and cardiac complications of long COVID." (PMID 37737732, 2023). "We found that both infected and bystander (not infected) BALF epithelial cells of severe COVID-19 patients presented upregulation of mTOR signaling genes, including SQSTM1 and CDKN1A." (PMID 36661509, 2022). "Finally, in clinical studies of COVID-19 patients, serum levels of autophagic proteins, such as LC3, SQSTM1, and BECN1, predicted the severity of COVID-19 disease." (PMID 34440791, 2021). "More LC3B- and particularly P62-positive cells were identified in COVID-19 patient lung samples, which might be explained by increased MAP1LC3B and SQSTM1 mRNA levels or again by a reduced autophagic flux and protein accumulation." (PMID 34155207, 2021).
Hepatic steatosis (7 papers, 2017 to 2025). Steatosis is a term used to denote lipid accumulation within hepatocytes. "In models of hepatic steatosis, microtubule-associated protein 1B light chain-3-II (LC3-II) and SQSTM1/P62 levels were elevated in parallel to blockade of autophagic flux." (PMID 33330497, 2020). "This promptly led us to the idea that FXR activates the pro-survival signals through the upregulation of p62/SQSTM1 and, at the same time, suppresses hepatic steatosis through the upregulation of SHP." (PMID 28086800, 2017). "Consistent with this, genetic ablation of core autophagy genes leads to the accumulation of ubiquitinated proteins and p62/SQSTM1-positive inclusions, oxidative stress, hepatomegaly, and hepatic steatosis, underscoring the role of autophagy in maintaining liver function." (PMID 41256541, 2025). "Liraglutide ameliorates hepatic steatosis by inducing activation of the TFEB-mediated ALP through modulation of LC3-II and SQSTM1/P62 autophagy substrates expression levels." (PMID 39175576, 2024). "Herein, MG increased ATG5-12, ATG7, Beclin1, ULK1, and LC3-II/I ratio and decreased p62/SQSTM1 and p-mTOR in the liver of Tylo-injected rats and PA-stimulated HepG2 cells, suggesting that MG might promote the formation of autophagic flux to alleviate hepatic steatosis." (PMID 32992548, 2020). "This study is the first to show the critical roles of the FXR-p62/SQSTM1 pathway in the protection against post-PH liver injury and possibly the FXR-SHP pathway in the improvement of liver steatosis." (PMID 28086800, 2017). "In a NAFLD mouse model and a PA-induced HepG2 cell model, liraglutide has been observed to alleviate hepatic steatosis by modulating the expression of autophagy substrates LC3-II and SQSTM1/P62, thereby activating the autophagy-lysosomal pathway (ALP) regulated through the TFEB pathway." (PMID 39175576, 2024). "On the other hand, in methionine/choline-deficient diet-induced NASH, autophagy-related proteins such as BECN1 and SQSTM1/p62 are upregulated, but autophagic flux is impaired by hypoxia-inducible factor-1 alpha (HIF-1α), which induces liver steatosis and inflammation." (PMID 33879861, 2021).
Huntington disease (7 papers, 2017 to 2022). Huntington disease (HD) is a rare neurodegenerative disorder of the central nervous system characterized by unwanted choreatic movements, behavioral and psychiatric disturbances and dementia. "Ubiquitin, p62/SQSTM1, and ubiquilin 2 (UBQLN2) are components of intracellular inclusions in a number of neurodegenerative diseases, including Huntington disease and C9ORF72-associated ALS/FTD." (PMID 31665086, 2019). "Elsewhere, an inability to complete autophagy leads to the accumulation of ubiquitinated and aggregate-prone polypeptides in the cytoplasm, including p62/SQSTM1, α-synuclein as well as the Huntingtin protein in Huntington’s disease." (PMID 29473871, 2018). "Importantly, HTT, whose expression is abrogated by the pQ expansion in Huntington’s disease, was recently found to facilitate selective autophagy by acting as a scaffold between autophagy adaptor p62/SQSTM1 and core autophagy molecules such as Atg1/ULK1 and Atg8/LC3 proteins." (PMID 28737703, 2017).
lung adenocarcinoma (7 papers, 2016 to 2024). A carcinoma that arises from the lung and is characterized by the presence of malignant glandular epithelial cells. "Furthermore, the loss of SQSTM1 suppressed Ras-induced lung adenocarcinoma." (PMID 27145374, 2016). "In this report, we present the case of a 60-year-old female diagnosed with advanced lung adenocarcinoma harboring the rare SQSTM1-ALK fusion, which had metastasized to the pericardium." (PMID 39555099, 2024). "This study presents the inaugural successful treatment of lung adenocarcinoma patients positive for SQSTM1-ALK with pericardial effusion using ensartinib." (PMID 39555099, 2024). "This suggests that the presence of the SQSTM1-ALK fusion in lung adenocarcinoma may lead to rapid progression, emphasizing the need for prompt and aggressive treatment strategies." (PMID 39555099, 2024). "Indeed, human lung adenocarcinoma A549 cells incubated with the purified anti-SQSTM1 sdAb clone #1 resulted in more LC3B-II accumulation upon trehalose (Tre, an autophagy enhancer) treatment, compared with the sdAb Con treatment." (PMID 34675071, 2022). "This suggests that Ensartinib may be a promising therapeutic option for lung adenocarcinoma patients with the SQSTM1-ALK fusion, though complete remission (CR) was not achieved during the observation period." (PMID 39555099, 2024). "The absence of p62/SQSTM1 inhibits ras-induced lung adenocarcinomas and increased cell death." (PMID 27588471, 2016).
oral cancer (7 papers, 2013 to 2024). "We performed autophagy fluorescence analysis to observe formation of autophagosomes and Western blot assay to confirm the involvement of cytoplasmic microtubule-associated protein 1A/1B-light chain 3 and p62/SQSTM1 proteins in oral cancer cells." (PMID 33921647, 2021). "The association between p62/SQSTM1 excess and prognosis was addressed in a clinical cohort of oral carcinoma cases." (PMID 24086340, 2013). "Therefore, the present study focused on understanding the association between GSSG-GSH and p62/SQSTM1 in X-ray irradiated oral cancer cells producing ROS." (PMID 24086340, 2013). "Finally, in order to clarify whether excessive p62/SQSTM1 could be associated with a clinically poor prognosis in oral cancer cases, the cohort study was performed." (PMID 24086340, 2013). "The embelin-induced autophagic cell death of oral-cancer cells was mediated by LC3-II and the suppression of p62/SQSTM1 and Beclin-1, and was associated with cleavage formation of the Atg5-Atg12 complex and Beline-1." (PMID 29522451, 2018). "In order to precisely explore a p62/SQSTM1 contribution to the Nrf2 pathway in oral epithelial carcinogenesis, p62/SQSTM1 knockdowns were designed in oral cancer cells, where p62/SQSTM1 was highly expressed." (PMID 24086340, 2013). "The oral cancer cell growth was inhibited by p62/SQSTM1 knockdowns especially under X-ray irradiated conditions." (PMID 24086340, 2013). "In order to analyze the contribution of p62/SQSTM1 to carcinogenesis in oral carcinoma cases, expressional evaluation of p62/SQSTM1 was performed immunohistochemically." (PMID 24086340, 2013). "p62/SQSTM1 was highly expressed in oral cancer cells of SAS and CAL27 compared with expression in human fibroblasts (TIG-108 and -121)." (PMID 24086340, 2013). "In order to analyze whether more ROS was accumulated in p62/SQSTM1-knockdown cells, ROS levels were quantified in the knockdown and control variants of SAS and CAL27 oral cancer cells." (PMID 24086340, 2013). "The immunohistochemical status of p62/SQSTM1 could predict the clinical prognosis of oral cancer cases, and the cases with strong p62/SQSTM1 staining showed the worse prognoses with regard to a 2-year survival." (PMID 24086340, 2013). "Specifically, p62, also known as sequestosome-1 (SQSTM1), is upregulated in human cancer, exhibiting an evident expression in pancreato-biliary, mammary, and oral cancer." (PMID 39131899, 2024). "In oral cancers, many pure compounds and phytochemicals have been reported to induce cell autophagy effectively through increased LC3 and p62/SQSTM1." (PMID 33921647, 2021). "In other words, p62/SQSTM1 excess cannot play a role in Nrf2 accumulation, but it instead helps to sustain GSH concentration in response to ROS in the oral cancer cells." (PMID 24086340, 2013). "Moreover, another cohort from the TCGA database found that oral cancer patients with high co-expression of EGFR and SQSTM1 had poor DSS (AHR = 2.53, 95% CI = 1.46–4.39, p = 0.001) but not DFS." (PMID 34830108, 2021). "We found that the Y341A L344A mLIR successfully reinstated autophagic substrate (SQSTM1) levels alongside mitochondrial proteins (TOMM20 and COX4I1) when compared to wild-type CLU, signifying the ineffectiveness of the CLU LIR mutant in eliciting cisplatin-induced mitophagy in oral cancer cells." (PMID 38447939, 2024). "However, p62/SQSTM1 expression has never been evaluated in oral carcinomas and epithelia, and the contributed functions have never been analyzed in oral epithelial carcinogenesis." (PMID 24086340, 2013). "Apoptotic cell death could not be detected under X-ray irradiated conditions in oral cancer cells, but the prominent accumulation of >G2/M phase cells was shown especially in p62/SQSTM1-knockdown cells, suggesting catastrophic growth-inhibition." (PMID 24086340, 2013). "Under no irradiation, GSH levels were mildly affected by p62/SQSTM1 knockdown in oral cancer cells." (PMID 24086340, 2013).
oral cancer (continued). "Therefore, the protein level of SQSTM1 may not be a sensitive indicator for determining autophagic activity in oral cancer cells exposed to LPLI." (PMID 27632526, 2016).
oral squamous cell carcinoma (7 papers, 2013 to 2024). "Studies have shown that MAP1LC3B and its adaptor sequestosome 1 (SQSTM1) modulate autophagy for tumorigenesis and prognosis in certain subsites of oral squamous cell carcinoma." (PMID 38240686, 2024). "In the present study, p62/SQSTM1 excess was demonstrated in the oncogenic progression of oral squamous cell carcinoma, but Nrf2 was expressed in almost all samples of the oral epithelium." (PMID 24086340, 2013). "Immunohistochemical evaluation of p62/SQSTM1 may prove to be a potentially significant test that will help to identify early carcinogenesis, chemo-radiotherapeutic resistance or poor prognosis of oral squamous cell carcinomas." (PMID 24086340, 2013). "Taken together, the results indicated that excessive p62/SQSTM1 was more significantly prominent in oral squamous cell carcinomas than in low grade dysplasias or non-atypical epithelia." (PMID 24086340, 2013).
cystinosis (6 papers, 2015 to 2024). Cystinosis is a metabolic disease characterized by an accumulation of cystine inside the lysosomes, causing damage in different organs and tissues, particularly in the kidneys and eyes. "De Leo and co-workers identified impaired autophagic flux and an increase in the amount of SQSTM1 proteins (which are linked to autophagy) as nephropathic cystinosis markers." (PMID 38540351, 2024). "With this lag in mind, De Leo and colleagues recently identified small molecule drug candidates that decrease the accumulation of the autophagy substrate p62/SQSTM1 and restore the autophagy–endolysosome degradative pathways, which are compromised in different models and cell systems of cystinosis." (PMID 35159136, 2022). "In cystinosis, there is an increase of the autophagosome marker (LC3-II and SQSTM1/p62) levels in cells which is reminiscent of autophagic flux dysfunction." (PMID 30717078, 2019). "Furthermore, in vivo cystinosis studies reported abnormal levels of autophagy, with changes in the expression of key autophagy genes such as TFEB, LC3II, and SQSTM1." (PMID 35011739, 2022). "As shown in Fig3A, starvation induced degradation of SQSTM1/p62 in both WT and Ctns−/− fibroblasts further supporting that autophagic flux is not impaired in cystinosis." (PMID 25586965, 2015).
head and neck squamous cell carcinoma (6 papers, 2021 to 2025). A squamous cell carcinoma that arises from any of the following anatomic sites: lip and oral cavity, nasal cavity, paranasal sinuses, pharynx, larynx, and salivary glands. "In head & neck squamous cell carcinoma cells, the autophagic cargo adapter p62/SQSTM1 is augmenting the activation and full processing of caspase 8 by capturing ubiquitinated caspase 8 into aggresome-like structures, necessary for subsequent apoptosis induction upon radiation treatment." (PMID 36596765, 2023). "Additionally, neferine isolated from Nelumbo nucifera promoted apoptosis through the accumulation of p62/SQSTM1 by inhibiting autophagic flux in head and neck squamous cell carcinoma." (PMID 36355504, 2022). "Firstly, we inspected the correlation of the expression of LUC7L2 and SQSTM1 in Head and neck squamous cell carcinomas (HNSCC) using The Cancer Genome Atlas (TCGA) database (n = 502)." (PMID 34907164, 2021).
liver fibrosis (6 papers, 2020 to 2025). "Depletion of CAV1 attenuates hepatic fibrosis by promoting SQSTM1-mediated PFKL degradation in hepatic stellate cells." (PMID 40303344, 2025). "Autophagy impairment mediated by TRIB3 and the selective autophagy receptor SQSTM1 in human liver fibrosis promoted the secretion of harmful exosomes, which induced the migration, proliferation and activation of HSCs." (PMID 33506641, 2021). "For example, stress-induced tribbles pseudokinase 3 (TRIB3) interacted with sequestosome 1 (SQSTM1) to enhance the secretion of INHBA/Activin A-rich exosomes from hepatocytes, thereby activating hepatic stellate cells (HSCs) and promoting liver fibrosis." (PMID 40771315, 2025).
nasopharyngeal carcinoma (6 papers, 2016 to 2025). A carcinoma arising from the nasopharyngeal epithelium. "Downregulation of MEG3 also promoted sequestosome 1 (SQSTM1) expression in nasopharyngeal carcinoma cells and is responsible for the increased migration, invasion and EMT in NPC cells." (PMID 40176927, 2024). "Downregulation of LUC7L2 in radioresistant nasopharyngeal carcinoma cells leads to suppression of sequestosome 1 (SQSTM1 or p62), expression and elevation of autophagy level." (PMID 39075259, 2024). "In primary ovine fetal turbinate (OFTu) cells and human nasopharyngeal carcinoma (NPC) cells, ORVF infection induces autophagy, which is characterized by the formation of autophagosomes and autolysosomes, increased LC3 lipidation and decreased SQSTM1 expression." (PMID 40937439, 2025).